CDKN2A (cyclin dependent kinase inhibitor 2A)
Diseases named in the same sentence as CDKN2A in open-access papers (continued):
Sharing a sentence is not in itself a finding about the gene and the disease.
melanoma (continued). "qRT-PCR analysis showed significant downregulation of CDKN2A expression in all melanoma cell lines examined when compared with the HEM melanocyte line." (PMID 39138582, 2024). "In the case of familial melanoma, germline mutations in certain high-risk genes, such as CDKN2A and CDK4, significantly increase the likelihood of developing melanoma, often at a younger age and with a higher propensity for multiple primary melanomas." (PMID 39518584, 2024). "Another key pathway in melanoma pathogenesis is related to the cyclin-dependent kinase inhibitor 2A (CDKN2A)." (PMID 39519202, 2024). "This assumption was supported by the previously obtained results, which showed a 61.53% percentage of CDKN2A-wt tumors in males and a 50% allocation of CDKN2A-mut melanomas among females." (PMID 38667459, 2024). "This difference disappeared in metastases, indicating that TPMs arise after CDKN2A inactivation in these melanomas." (PMID 38371417, 2024). "Genetic changes in CDKN2A are linked to multiple primary melanomas (MPM), with patients diagnosed with melanoma facing an elevated risk of developing additional primaries." (PMID 38792946, 2024). "The triple-score cut-off of 9 was noted to differentiate homozygous CDKN2A deletion melanomas from CDKN2A-wild type and heterozygous deletion tumors." (PMID 38667459, 2024). "Frequently denoted as p16 or INK4a/ARF, mutations in the CDKN2A gene are a less commonly explored aspect within the context of melanoma when compared to BRAF alterations." (PMID 38792946, 2024). "When there are borderline features, molecular assessment for the presence of additional mutations, such as CDKN2A or TERT-p, and chromosomal CNA can be helpful in differentiating low-CSD melanomas from intermediate lesions." (PMID 38247727, 2024). "Approximately 40% of familial melanoma cases are characterized by the mutation of the CDKN2A gene that determines defects in the p14 ARF and p16 INK4A proteins that are essential in controlling cell cycle arrest." (PMID 39063046, 2024). "Downregulating CDKN2A in BRAF-inhibitor-resistant melanoma cells improves the effectiveness of palbociclib." (PMID 38534309, 2024). "Such heterogeneity was reported before, but the main focus was on the MAPK pathway and melanoma-related oncogenic pathways and tumor suppressors, such as PI3K, PTEN, AKT, and CDKN2A, or amplification of BRAF and mutations of the RAS family." (PMID 39001376, 2024). "In the context where the detection limit of melanomas with homozygous CDKN2A deletion is set to a total value of at least 9, the sensitivity of the test is 100%, and the specificity is 94.11%." (PMID 38667459, 2024). "These motivations were in line with a previous cohort study of Australian family members with hereditary melanoma due to a CDKN2A PV." (PMID 38822936, 2024). "This cyclin-dependent kinase inhibitor gene was mapped to the same chromosomal region as the R/Diff effect, and its human ortholog (CDKN2A) is a well-known tumor suppressor that is frequently affected, particularly in melanoma." (PMID 38299666, 2024). "Germline mutations of CDKN2A, CDK4, TERT, and POT1 genes have been identified as high-risk factors for melanoma susceptibility, whereas MC1R (melanocortin 1 receptor) polymorphic variants are reported in 60.5–82.1% of melanoma." (PMID 38473275, 2024). "With the accumulation of more genetic mutations, such as mutations in the CDKN2A, TP 53, PTEN, or others, the lesion becomes invasive, that is, malignant melanoma." (PMID 39063046, 2024). "Mutations or deletions in CDKN2A/B genes and amplification of CDK4 are commonly observed in melanoma, contributing to uncontrolled cell proliferation and tumor growth." (PMID 38982214, 2024).
melanoma (continued). "CDKN2A is a tumour suppressor gene associated with FAMMMS (OMIM #155601), melanoma-pancreatic cancer syndrome (OMIM #606719) and Melanoma and neural system tumour syndrome (OMIM# 155755)." (PMID 39021548, 2024). "Cell-cycle control is another major aspect of melanoma regulation, the cyclin-dependent kinase inhibitor CDKN2A encodes P16 and P14ARF proteins, both of which can be mutated, deleted, or silenced in melanoma." (PMID 39234260, 2024). "Cyclin-dependent kinase inhibitor 2A (CDKN2A), encoding the two tumor-suppressor proteins p14ARF and p16INK4a, belongs to the most frequently inactivated gene loci in melanoma and leads to decreased T cell infiltration." (PMID 38807304, 2024). "The CDKN2A (cyclin-dependent kinase inhibitor 2A) gene is frequently deactivated as a tumor suppressor gene in melanoma." (PMID 38534309, 2024). "Studies have also shown that the likelihood of developing melanoma in CDKN2A carriers varies across geographical areas and increases with age." (PMID 39195270, 2024). "For skin cancer, previous studies have assessed the benefits and harms of genetic testing for cyclin-dependent kinase inhibitor 2A (CDKN2A)—the major high-penetrance gene for melanoma —among members of melanoma-prone families." (PMID 39682213, 2024). "NR-V04 treatment effectively inhibited tumor growth in the MC38 model and Yummer1.7 melanoma (generated from a tumor formed in a BrafV600/Cdkn2a−/−/Pten−/− mouse), as well as the commonly used B16F10 melanoma model." (PMID 38334978, 2024). "Taken together, these results indicate that expression of miR-876 is downregulated in a substantial proportion of melanoma cell lines, along with reduced expression of CDKN2A in the same cell lines." (PMID 39138582, 2024). "The targeted deletion of Cdkn2a in vertebrates presents an optimal melanoma model for recapitulating the progression of CDKN2A-HM." (PMID 39659584, 2024). "The main difference is that DPN-like melanomas often harbor additional genetic alterations, including TERT-p mutations and inactivation of CDKN2A." (PMID 38247727, 2024). "Losses of the CDKN2A gene, which resides on 9p21, have been shown in a substantial proportion of both familial and sporadic melanomas." (PMID 39138582, 2024). "Melanocytic nevi, typically benign, can evolve into melanoma through mutations, primarily BRAFV600E in common nevi and various mutations in MAPK signaling, the TERT promoter, and CDKN2A in dysplastic nevi." (PMID 38474231, 2024). "On the way to low-CSD melanoma, cells first encounter OIS, which is overcome by loss of CDKN2A and subsequently leads to telomere shortening followed by immortalization." (PMID 38371417, 2024). "In human CDKN2A-mutant melanomas, the disrupted binding of inactive p16INK4a to p65 leads to NF-kB transcriptional activation." (PMID 39659584, 2024). "Disabling CDKN2A enhances the susceptibility to CDK4/6 inhibitors in certain types of cancer cells, such as melanoma." (PMID 38534309, 2024). "We found that the expression of FDX1, LIAS, LIPT1, DLD, DLAT, MTF1, and CDKN2A were significantly lower in melanoma than in normal tissues." (PMID 36824136, 2023).
melanoma (continued). "In a cohort study comprised of 7119 melanoma patients, 40 cases (0.6%) were identified with activated RAF1 structural variants accompanied by mutations in TERTp and CDKN2A." (PMID 38111008, 2023). "Three pathogenic variants (PVs) in melanoma predisposition genes were found (MITF p.Glu318Lys and CDKN2A p.Gly101Trp in #56 and MITF p.Glu318Lys in #62)." (PMID 36901733, 2023). "As the previous studies reported, CDKN2A is an unstable gene and appeared alteration in various types of cancer, including pancreatic cancer, esophageal cancer, head and neck cancer, melanoma, bladder cancer, glioma, lung cancers, and etc. al.." (PMID 37857018, 2023). "What more, CDKN2A alteration is reported to be related to immunity therapy resistance and small molecular target drug resistance in lung cancer, melanoma, and breast cancer." (PMID 37857018, 2023). "In the context of melanoma, deletions in CDKN2A appear to attenuate the efficacy of immune checkpoint inhibitors." (PMID 37936609, 2023). "Germline mutations in CDKN2A leading to loss of function and/or CDK4 activating mutations are associated with a 50-fold increased risk of melanoma, according to a study of familial melanoma." (PMID 37081962, 2023). "We modeled BRAFV600E and NRAS-mutant tumors, which form most patient cutaneous primary melanomas in the clinic, and considered a range of further molecular alterations, namely, MITF status, loss of PTEN, presence of BRAFV600E, and loss of CDKN2A." (PMID 37043573, 2023). "For example, CDKN2A and BAP1 germline mutations predispose melanoma and mesothelioma, while CDKN2A and HRAS were frequently mutated in vulvar squamous cell carcinoma." (PMID 37626750, 2023). "Epigenetic silencing has specifically been reported for important tumor suppressors in melanoma such as CDKN2A (p16) and CDKN2B (p15)." (PMID 37834158, 2023). "The peptide is based on the target-binding site of the melanoma suppressor and senescence effector p16 (also known as INK4A or CDKN2A), coupled to a cell-penetrating moiety." (PMID 37522264, 2023). "The genetic underpinning of melanoma was established by identification of somatic BRAF and germline CDKN2A mutations in cutaneous melanoma and familial melanoma, respectively." (PMID 37841001, 2023). "We therefore employed the YUMMER1.7 melanoma cell line, which has a mutation in BRAF and loss of PTEN and CDKN2A along with additional radiation-induced mutations." (PMID 36821392, 2023). "Immunohistochemical analysis showed that compared with normal tissues, the protein level of CDKN1A was significantly down-regulated in melanoma, while the CDKN2A protein level was significantly up-regulated." (PMID 38070141, 2023). "It is thought that the onset of de novo melanoma in these patients is caused by genetic factors related to the FAMMM syndrome, as genetic analyses often reveal CDKN2A mutations associated with this syndrome." (PMID 36676131, 2023). "Only serum CXCL10 levels exhibited significant differences across patients harboring melanomas with different mutations (BRAF, CDKN2A, NF, NRAS)." (PMID 37435077, 2023). "For example, CDKN2A germline mutation dramatically increases both melanoma risk and risk of multiple dysplastic nevi, but the percentage of NAM in CDKN2A germline patients is similar to the general population." (PMID 36834954, 2023).
melanoma (continued). "Melanoma-pancreatic carcinoma syndrome, also known as familial atypical multiple mole melanoma syndrome (FAMMM), is a rare inherited syndrome caused by CDKN2A mutations, which have a prevalence of <0.1% in the whole population." (PMID 37370677, 2023). "Using DISCOVER analysis we identified eight statistically significant mutually exclusive genetic interactions, six with BRAF and two with CDKN2A, each representing important insights into the pathways through which melanoma develops." (PMID 36219477, 2023). "Deletion of CDKN2A was the most common copy number event in primary melanoma: 63% of samples showed copy number losses affecting CDKN2A, with 13% showing homozygous deletions across the entire gene." (PMID 36219477, 2023). "The tendency to develop multiple melanomas at an early age is another clinical feature that CDKN2A patients share." (PMID 37568588, 2023). "The gene PRDM2 showed a mutation pattern of mutual exclusivity with CDKN2A and is of particular interest since PRDM2 is a binding partner of RB1, a well‐established melanoma driver." (PMID 36219477, 2023). "The highest mutation frequency of BRAF, ATRX, IDH1, CDKN2A, and EGFR was seen in melanoma (SKCM), thyroid carcinoma (THCA), brain lower-grade glioma (LGG), head and neck squamous cell carcinoma (HNSC), and glioblastoma multiforme (GBM), respectively." (PMID 37000317, 2023). "CDKN2A, CDK4, and BRCA1-associated protein 1 (BAP1) have been identified as high-risk melanoma susceptibility genes." (PMID 37504268, 2023). "Germline pathogenic variants (GPVs) in melanoma susceptibility genes CDKN2A, CDK4, and BAP1 are identified in up to 40%, 0.7%, and 1.0% of familial melanoma cases, respectively." (PMID 36876055, 2023). "In this respect, several high-penetrance genes such as CDKN2A, CDK4, or BAP1 are the most mutated in hereditary melanomas." (PMID 37958863, 2023). "In our study cohort, we found three PVs in melanoma predisposition genes in two patients (MITF p.Glu318Lys and CDKN2A p.Gly101Trp in #56 and MITF p.Glu318Lys in #62)." (PMID 36901733, 2023). "CDKN2A expression is correlated with the development and prognosis of various tumours, including hepatocellular carcinoma, pancreatic cancer and melanoma." (PMID 36699463, 2022). "Sequencing analysis of a patient with multiple schwannomas and melanomas identified a novel duplication in the coding region of CDKN2A, disrupting both p14ARF and p16INK4a." (PMID 35723634, 2022). "Similar results were obtained in PDX models of BRAF-V600E-mutant melanoma refractory to BRAFi/MEKi therapy which harbored mutations in NRAS and CDKN2A." (PMID 35565444, 2022). "Specifically, the cells chosen were the BrafV600E, Pten−/−, and Cdkn2a−/− male melanoma mouse line, YUMM 1.7, and the UV-irradiated YUMMER 1.7 with a higher mutational burden than YUMM 1.7, along with the human melanoma SK-MEL−28 cell line." (PMID 35336014, 2022). "We detected mutations in six genes in the EVs (BRAF, NRAS, CDKN2A, STK19, PPP6C, and RAC), and at least one mutation was detected in all melanoma EV samples." (PMID 36531960, 2022). "The highest proportion of familial malignant melanoma cases arises from the mutations in the CDKN2A gene, which codes for two tumor-suppressor proteins, p14ARF and p16INK4a." (PMID 35465855, 2022). "TargetSeq identified genetic aberrations in 11 genes among them expected drivers of melanoma progression such as CDKN2A." (PMID 36435874, 2022). "Here, we report a family with CDKN2A c.301G>T mutation who had multiple oral squamous cell cancers (OSCC) and melanoma." (PMID 35123577, 2022). "Of note, others have shown that CDKN2A deletion activates mTOR in melanoma tumors and induces S6 phosphorylation." (PMID 35385746, 2022).
melanoma (continued). "In melanoma, activating mutations in CDK4 abolish interactions with the tumor suppressor Cyclin dependent kinase inhibitor 2 A’s (CDKN2A) / p16INK4A, rendering the protein constitutively active, leading to uncontrolled cell cycling." (PMID 34759345, 2022). "Particularly, germline whole gene deletions of CDKN2A and CDKN2B are known to be associated with familial syndromes predisposing to malignant melanoma as well as other nervous system tumors, including meningioma, astrocytoma, and schwannoma." (PMID 35723634, 2022). "CDKN2A PVs were frequent in patients with a family history of PC (8/55, 14.5%) and with a personal or family history of melanoma (6/30, 20%); however, the rate remains high (8/283, 2.8%) in sporadic subjects." (PMID 36139606, 2022). "Mutations in the BRAF gene are present in 50–60% of melanomas and the CDKN2A gene is altered in 16–41% of melanomas." (PMID 36143291, 2022). "Deletion of CDKN2A is a common feature in melanoma, which leads to down-regulation of downstream p14ARF expression." (PMID 36620597, 2022). "Germline pathogenic variants (PVs) in a number of genes predispose to melanoma, but the largest proportion of familial melanoma cases (20%-40%) are due to PVs in the gene CDKN2A (cyclin-dependent kinase inhibitor 2A)." (PMID 35372037, 2022). "For example, the RB1 pathway is a primary driver of skin cancers, with mutations in RB1, CDKN2A/p16, CDKN1A/p21, CDKN1B/p27, CDKN2B/p15, CCNE1/cyclin E, and CCND1/cyclin D, collectively, in 26.4% of melanomas." (PMID 34983823, 2022). "Of note, several CDKN2A patients have been reported with melanomas with coexisting BRAF and NRAS mutations, which is uncommon in sporadic melanomas." (PMID 35372037, 2022). "Germline CDKN2A mutations are a well-known cause of familial atypical multiple mole melanoma (OMIM #155601) and melanoma-pancreatic cancer syndrome (OMIM #606719)." (PMID 35123577, 2022). "CDKN2A functions as a tumor suppressor gene, and somatic CDKN2A PVs are commonly found in both sporadic and hereditary melanomas." (PMID 35372037, 2022). "An additional five cases displayed clinically pathogenic variant in three genes predisposing to either melanoma or RCC, namely FLCN (N = 2), CDKN2A (N = 2), and PTEN (N = 1)." (PMID 34067022, 2021). "Other common mutations found in melanoma are NRAS (neuroblastoma RAS viral oncogene homolog), c-Kit and CDKN2A (cyclin dependent kinase inhibitor 2A) the latter of which associates with familial atypical multiple mole melanoma syndrome (FAMMM)." (PMID 35127523, 2021). "From the available NGS data of our cases, copy number variants affecting CDKN2A and KIT are frequently seen in mucosal melanomas." (PMID 34571863, 2021). "This high phosphorylation capability of mutant BRaf, when couples with the mutant P16/INK4a as the result of cyclin-dependent kinase inhibitor 2A (CDKN2A) mutation or phosphatase and tensin homolog (PTEN) mutation, can lead to melanoma development." (PMID 33692796, 2021). "We first looked at an extended list of high-risk genes predisposing to melanoma (ACD, CDKN2A, CDK4, POT1, TERF2IP, and TERT) or RCC (CDKN2B, FH, FLCN, MET, PBRM1, PTEN, SDHs, TSCs, and VHL) or both (BAP1 and MITF)." (PMID 34067022, 2021). "Desmoplastic melanomas have fewer DNA copy number alterations than other melanoma subtypes; nevertheless, the few focal deletions that have been observed targeting CDKN2A and NF1." (PMID 34441278, 2021).